TET1 (tet methylcytosine dioxygenase 1)
Diseases named in the same sentence as TET1 in open-access papers (continued):
Sharing a sentence is not in itself a finding about the gene and the disease.
breast (5 papers, 2016 to 2021). "Of note, the increase in Tet1 levels after liver injury in vivo (day 3 following DDC treatment) was only transient, since Tet1 expression decreased at the peak of DDC-mediated liver damage (day 5)." (PMID 33732709, 2021).
hematological malignancies (4 papers, 2021 to 2023). "Although genes encoding TET1 and TET3 are rarely mutated in hematopoietic diseases, TET2 frequently undergoes somatic mutation, affecting both lymphoid and myeloid lineages." (PMID 36675240, 2023). "Previous studies revealed that loss-of-function mutations of TET2 are frequently found in hematological malignancies, while the mutations of TET1 are not." (PMID 33705482, 2021). "In hematological malignancies, loss-of-function mutations of TET2, which is one of the TET family genes including TET1, are frequently found, while the mutations of TET1 are not." (PMID 33705482, 2021). "Notably, in an assay to quantify 5hmC in the genome of patients with various hematologic malignancies, levels of 5hmC in a significant proportion of patients with wild-type (WT) TET2 (and also WT TET1 and TET3) were as low as those from patients with TET2 mutations." (PMID 36675240, 2023).
metabolic disease (3 papers, 2021 to 2025). A congenital disorder (due to inherited enzyme abnormality) or acquired (due to failure of a metabolically important organ) disorder resulting from an abnormal metabolic process. "TET1 also plays a fundamental role in regulating glucose metabolism, with implications for the treatment of metabolic disorders." (PMID 40520993, 2025). "In recent years, the role of TET1 in metabolic diseases has received increasing attention." (PMID 41152554, 2025). "Collectively, our study identifies TET1 as a SIRT1 coactivator and demonstrates that the AMPK-TET1-SIRT1 axis represents a potential mechanism or therapeutic target for glucose metabolism or metabolic diseases." (PMID 34738906, 2021).
neurological diseases (3 papers, 2020 to 2023). "Thus, by combining different epigenetic effector domains, such as DNMT3 and Tet1, with dCas9, therapeutic epigenetic editing acts as a promising therapeutic tool for various neurological diseases, including FXS, ALS, and PD, with minimal side effects." (PMID 36109806, 2022).
adenocarcinoma (2 papers, 2021 to 2022). A common cancer characterized by the presence of malignant glandular cells. "Analysis of the genes differentially expressed in this cohort of 887 adenocarcinomas revealed that TET1, but not TET2 or TET3, was strongly downregulated in tumors since stage I. This indicates that TET1 downregulation is an early event in colon tumorigenesis." (PMID 35269796, 2022).
cardiovascular disease (2 papers, 2022 to 2025). "TET1 appears to play a protective role in cardiovascular disease, particularly in atherosclerosis." (PMID 40520993, 2025). "The H19/TET1 axis likely plays a crucial role in endothelial-to-mesenchymal transition and may contribute to the development of cardiovascular disease, presenting a potential therapeutic avenue for further investigation." (PMID 40520993, 2025). "However, the precise role of TET1 in cardiovascular disease remains undefined." (PMID 35342333, 2022).
neurodegenerative disease (2 papers, 2024). A disorder of the central nervous system characterized by gradual and progressive loss of neural tissue and neurologic function. "It has been reported to differentiate neural stem cells into dopaminergic neurons via upregulating the TET1 and FoxA2 expression and their binding, indicating potential application as neural stem cell replacement therapy for neurodegenerative diseases." (PMID 38505421, 2024).
hematologic neoplasms (1 paper, 2023). "Given that most patients with hematologic neoplasms are TET2 haplodeficient and that TET1 and TET3 mutations are rare, it is likely that activating the residual TET2 or the other TET family members TET1 and TET3 may be a promising treatment strategy for TET2-deficient malignancies." (PMID 36979633, 2023).
inflammation (1 paper, 2022). Aberrant reaction of the microcirculation characterized by movement of fluid and leukocytes from the blood into extravascular tissues. "Our previous study found that Tet1 deletion enhanced HDM-induced lung inflammation in mice, and that it was linked to transcriptomic changes in proinflammatory molecules (Il33) and detoxification enzymes (Gsto1 and Aldh1a1) in total lung RNA." (PMID 35627266, 2022).
psychiatric disorder (1 paper, 2021). A disorder characterized by behavioral and/or psychological abnormalities, often accompanied by physical symptoms. "TET1 is closely associated with psychiatric disorders (e.g., schizophrenia, autism)." (PMID 34656178, 2021). "TET1 has been studied in stem cells, neuroregeneration, metabolism, ageing, and psychiatric diseases but not yet in depth." (PMID 34656178, 2021).
TET1 also shares sentences with these, for which no sentence is quoted: myeloproliferative neoplasm (5 papers); autism (3); Parkinson disease (3); Uterine leiomyoma (3); bipolar disorder (2); brain cancer (2); chronic myelocytic leukaemia (2); gastric adenocarcinoma (2); hematologic cancers (2); Intellectual disability (2); laryngeal carcinoma (2); myeloid malignancies (2); non-Hodgkin lymphoma (2); oral cancer (2); oropharyngeal cancer (2); Papillary Thyroid Carcinoma (2); paraganglioma (2); premature ovarian failure (2); rectal cancer (2); small intestinal neuroendocrine tumors (2); uterine cancer (2); acute leukemia (1); and lymphoid leukemias (1); ataxia telangiectasia (1); basal cell carcinoma (1); breast invasive carcinomas (1); Cerebral ischemia (1); cervical squamous cell carcinoma (1); chondrosarcoma (1); cognitive decline (1).
A further 54 diseases each share a sentence with TET1 in 1 paper.